C3 (complement C3)
Diseases named in the same sentence as C3 in open-access papers (continued):
Sharing a sentence is not in itself a finding about the gene and the disease.
amyloidosis (continued). "Furthermore, these Decorin+C3+ astrocytes maintain their phagocytic capacity and exhibit a neurotoxic gain of function and are associated with vascular amyloid deposits but not parenchymal amyloid plaques in mouse models and AD/CAA patients." (PMID 35351973, 2022). "Furthermore, C3 upregulation in astrocytes is not only the result of microglial inflammation, but the downstream cleavage product C3a can in turn dramatically increase the synaptic toxicity of microglia in mouse models of amyloidosis and tauopathy by binding to microglial C3aRs." (PMID 31277708, 2019). "Classical pathway proteins, including C1q, C3 and C4, co-localized specifically with amyloid plaques but not tangles in temporal cortex, amygdala, and hippocampus, the brain regions most affected in AD." (PMID 38505993, 2024). "Our findings collectively open new avenues for research into the proteome alterations in amyloid diseases and elucidation of several key proteins that have the potential to be leveraged as biomarkers for V30M ATTRv-PN, including TTR itself, CP, APOE, and the complement pathway proteins such as C3." (PMID 40564999, 2025). "Findings from cases with non-ICGN and amyloidosis were also quite consistent between IF-FFPE and IF-F, although there were some minor differences (IgG in cases 9 and 10; IgA, IgM, and C3 in case 12)." (PMID 29191199, 2017).
depression (32 papers, 2012 to 2026). "Mounting experimental evidence has shown that complement C3 signaling is associated with the pathogenesis of depression, and disruption of the gut microbiota may be an underlying cause of complement system activation." (PMID 38378622, 2024). "We hypothesize that depression is caused by dysbiosis of the gut microbiota and abnormal synaptic pruning of microglia mediated by complement C3." (PMID 38378622, 2024). "Research into the relationship between gut microbiota and neuroimmune mechanisms shows that gut dysbiosis induces depression-like behavior via complement C3-mediated abnormalities in microglial synaptic pruning." (PMID 40936908, 2025). "Recent research has shown that overexpression of complement C3 affects phagocytosis and synaptic pruning of microglia, leading to depression and abnormal cognitive behavior." (PMID 38378622, 2024). "The median serum concentrations of C3 were 93.03μg/mL, 64.77μg/mL in depression patients, healthy controls, respectively, with significant difference between the two groups." (PMID 38895030, 2024). "This suggests that the activation of C3/CR3 signaling is co-localized with microglia in the cytoplasm during the development of depression." (PMID 38378622, 2024). "The results of the control group ELISA showed that serum levels of TUBB, ITIH4, C3 and C4A were significantly higher in patients with depression than in healthy controls." (PMID 38895030, 2024). "The emergence of depression-like behavior and the mechanism of antidepressants involves changes in the gut microbiota, complement C3/CR3, and synaptic pruning." (PMID 38378622, 2024). "By regulating complement C3 and microglia involved in the gut-brain crosstalk pathway in the pathogenesis of depression, the inhibition of abnormal synaptic pruning becomes the key to targeting microbes to treat depression." (PMID 38378622, 2024). "Selective overexpression of complement C3 in the medial prefrontal cortex (mPFC) was sufficient to produce depression-like behavior in mice, while C3 and C3aR knockout mice were resilient to chronic stress-induced depressive-like behavior." (PMID 36765267, 2023). "Recent studies from clinical and animal models have identified a significant increase in complement C3 expression in the prefrontal cortex of depressed suicidal individuals and a stress-induced mouse model of depression." (PMID 36765267, 2023). "Given that sickness is a form of depression, this results suggest that C3/C3aR signaling is typically activated at pre-onset and onset stages of depression." (PMID 35715851, 2022). "C3/C3aR levels were detected at the pre-onset (6 h post LPS injection) and onset (24 h post LPS injection) of depression." (PMID 35715851, 2022). "The results showed that C3 and C3aR levels were typically elevated at 6 h (sickness) and 24 h (depression) post LPS injection." (PMID 35715851, 2022). "To verify if the activation of C3 signaling is a pre-onset index of depression, we assessed C3/C3aR in mice during the induction of depression and at the onset of depression." (PMID 35715851, 2022). "In the present study, the dynamic alteration of complement C3 and its receptor C3aR during the occurrence of depression and the mechanism of astrocyte-microglia IL-1R/C3/C3aR on synaptic pruning were investigated." (PMID 35715851, 2022). "In the present study, we firstly evaluated the dynamic alteration of complement C3 and C3aR in the early onset and throughout the course of depression." (PMID 35715851, 2022). "The deletion of complement C3 was shown to reduce pain-, anxiety-, and depression-like behaviors and to improve learning and spatial memory in aged mice." (PMID 33898422, 2021). "This study is aimed at investigating the clinical significance of changes in serum concentrations of melatonin (MT), interleukin-6 (IL-6), homocysteine (hcy), and complement C3 and C4 in depression patients and relationships of them with depression activity." (PMID 32655450, 2020).
depression (continued). "Levels of acute phase protein complement C3 are elevated in depression and are significantly higher in the atypical subtype compared to melancholic depression." (PMID 33255237, 2020). "Collectively, our results revealed that gut dysbiosis induces the development of depression-like behaviors through abnormal synapse pruning in microglia-mediated by complement C3, and the inhibition of abnormal synaptic pruning is the key to targeting microbes to treat depression." (PMID 38378622, 2024). "Data from mouse studies demonstrate elevated C3 expression in postmortem PFC participants, implying that C3 may play a role in the synaptic loss seen in depression patients." (PMID 37884917, 2023). "The role of C3-mediated synaptic pruning in neuroinflammation is well documented; therefore, we tried to investigate whether C3-mediated synaptic pruning was also induced in depression and if it was prevented by Gypenoside XVII." (PMID 35745148, 2022). "The current study demonstrates that astrocyte-microglia IL-1R/C3/C3aR activation causes the abnormal synaptic pruning in depression, and suggests that the activation of complement C3/C3aR may be particularly helpful in predicting the onset stage of depression." (PMID 35715851, 2022). "Interestingly, increased levels of the complement factors C3 and C4 have been observed in patients with depression compared to controls." (PMID 23209684, 2012). "However, the mechanism by which complement C3 participates in gut-brain crosstalk in the pathogenesis of depression remains unknown." (PMID 38378622, 2024). "Besides acting as an essential immune regulator, C3 also regulates the development of depression." (PMID 36793870, 2023). "However, it remains unclear if complement C3/C3aR activation could be served as one of the distinguishing features in depression." (PMID 35715851, 2022). "Interestingly, among the anxiety- and depression-related DEGs, we found the upregulation of Bcl3, C3, Gpat3, and Tnf in the AMY as well as the increased expression of Crhr2, Nant, Sar1a, and Tgif1 and the decreased expression of Ier2, Il12a, Nrep, and Tnfrsf25 in the ACC." (PMID 33898422, 2021). "The following 16 parameters showed a statistical difference between AIH patients with and without cirrhosis: age, ALB, GLO, ALT, AST, ALP, WBC, Hb, PLT, IgG, C3, C4, ANA titer, and comorbidities such as depression, extrahepatic AIDs, and enlarged ALN." (PMID 41503678, 2026). "In the present study, we demonstrated that gut microbiota dysbiosis induces C3/CR3 system activation to promote synaptic pruning and precipitate depression-like behaviors." (PMID 38378622, 2024). "Our findings provide novel insights into the involvement of complement C3/CR3 signaling and aberrant synaptic pruning of chemotactic microglia in gut-brain crosstalk in the pathogenesis of depression." (PMID 38378622, 2024). "Collectively, these results indicate that complement C3/CR3 activation and microglia-mediated aberrant synaptic pruning are important pathological manifestations of depression." (PMID 38378622, 2024). "Research has also associated other pro-inflammatory biomarkers with mental health disorders and complement component 3 (C3), interleukin 6 (IL-6), leptin and white blood cell count (WBC) concentrations are reported to be higher in subjects with depression." (PMID 38560580, 2024). "Furthermore, the changes of serum C3 levels between first-episode and recurrent patients may imply that more researches are needed to be done in order to deeply understand the detailed mechanism of complement disorder in patients with depression." (PMID 32655450, 2020). "STRING software showed that ITIH4, C3, C4A and TUBB were involved in the pathogenesis of depression through an unknown pathway." (PMID 38895030, 2024).
depression (continued). "Our results showed that chronic stress, inducing depression-like behaviors in mice, led to increased levels of TNF-α, TNFR1, C3, CXCL1, and cleaved-caspase-3, indicating that astrocyte activation and neuronal apoptosis occurred during these depression-like behaviors." (PMID 38710713, 2024). "Researchers have found that chronic stress can lead to increased expression of C3 in the PFC of mice, and C3-KO mice do not develop depression-like behaviors, suggesting that a high level of C3 is an important condition for the onset of depression." (PMID 38378622, 2024). "The results also indicated that Gypenoside XVII from Gypenosides could regulate the complement system by attenuating the changes in the C3/C3aR/STAT3 signaling pathway and thus inhibiting synaptic pruning in stress-induced depression." (PMID 35745148, 2022). "Hao and his team found that germ-free mice exhibited elevated serum C3 and C3/C3R signaling after receiving a microbiome from the feces of mice with chronic unpredictable mild stress (CUMS), which resulted in abnormal microglia-dependent synapse pruning and signs of depression in those mice." (PMID 41398960, 2025). "Our results indicated that the levels of C3, TNF-α, and TNFR1 were increased in the CUMS mice, and TNF-α could activate primary astrocytes, suggesting that TNF-α may activate pro-inflammatory astrocytes by TNFR1 signaling pathways during depression." (PMID 38710713, 2024). "Anxiety and depression can be induced by immunological and neurotransmitter dysregulation, which is characterized by hypothalamic–pituitary–adrenal (HPA) axis dysfunction, production of proinflammatory cytokines, and activation of complement in the blood, such as C3 and C4." (PMID 37884917, 2023). "Therefore, PHL might act as a natural NF-κB pathway inhibitor to decrease the NF-κB-mediated C3 expression, suggesting the potential role of PHL in the prevention of depression." (PMID 36793870, 2023). "However, the studies did not elucidate how the C3/C3aR signaling activation mediates the production of cytokines and the pathophysiology of depression." (PMID 35715851, 2022). "Besides, the mechanism of complement C3/C3aR in neuronal and synaptic damage of depression is not understood." (PMID 35715851, 2022). "AIH patients with depression presented with higher serum levels of ALT, AST, and IgG and lower serum levels of C3 and C4 than those without depression (p = 0.002, p = 0.005, p < 0.001, p = 0.044, p = 0.003)." (PMID 41503678, 2026).
schizophrenia (32 papers, 2011 to 2026). A major psychotic disorder characterized by abnormalities in the perception or expression of reality. "Here, we aimed to investigate the association of C3, another critical factor in complement system, with schizophrenia in Chinese Han population." (PMID 26305563, 2015). "Also, it is worth exploring the effect of other immune-related players in the complement pathway (e.g., CSMD1, C1q, C3) on suicide risk in schizophrenia patients." (PMID 38341430, 2024). "Moreover, increased C1qA, C3, and C4 transcripts were reported to be associated with microglial activation in the midbrain of schizophrenia patients." (PMID 34831151, 2021). "However, one study pointed that individuals at ultra-high risk (UHR) for psychosis had elevated C3 and C4 protein levels, suggesting that alteration of complement system accompanied the development of schizophrenia." (PMID 34306006, 2021). "Among the complement proteins, the most studied in schizophrenia are the ones comprising the classical pathway, C1q, C2, C3, and C4." (PMID 40867623, 2025). "In patients with schizophrenia, significantly more complement protein was observed in EVs (namely C3, C4A, C4B, C4BPA, and C4BPB)." (PMID 40867623, 2025). "Some of the molecular signals such as C1q-C3 interaction have been revealed, and aberrant deposition of the complement C4 plays a role in pathological conditions such as schizophrenia." (PMID 39258226, 2024). "In schizophrenia, the gene expression of complement pathway activators (C1qA) and mediators (C3 or C4) was increased in the midbrain, especially in patients with inflammatory biotypes." (PMID 36845383, 2023). "In conclusion, genetic associations with schizophrenia were found for RCA, which regulate the complement activity by dissociating C3 and C5 convertases." (PMID 33670154, 2021). "The first study found a significantly increased activity for C2 (and C1, C1q, C3, C4) in schizophrenia patients compared to the healthy controls, whereas a second study found the C2 activity to be significantly lower in patients compared to the controls." (PMID 33670154, 2021). "We show, for the first time, increased gene expression of C1qA, C3, and C4 in the midbrain in schizophrenia in cases previously classified as having a high inflammatory status defined by cytokine gene expression." (PMID 33133060, 2020). "All of the complement pathways converge at the point of C3 and data related to C3 levels in blood from schizophrenia patients are also controversial." (PMID 32116493, 2020). "CUB and sushi multiple domains 1 (CSMD1) is a complement control-related gene that inhibits the activation of complement C3 and has a possible role in lupus erythematosus and schizophrenia." (PMID 32183058, 2020). "Another study revealed that serum concentrations of C3 and C4 in patients with BD were comparable to the levels in healthy individuals, but significantly lower than in schizophrenia patients." (PMID 30538645, 2018). "In particular, the C4 complement system is abnormal in schizophrenia; C4 activates C3, which binds to target spines and promotes their engulfment by phagocytic cells." (PMID 27136678, 2016). "Complement pathway activation was reported to occur frequently in schizophrenia, in which complement 3 (C3) regulates the process." (PMID 26305563, 2015). "Complement pathway activation was found to occur frequently in schizophrenia, and complement 3 (C3) plays a major role in this process." (PMID 26305563, 2015). "Peripheral C3 mRNA expression level was measured in 23 drug-naïve patients with schizophrenia and 24 controls." (PMID 26305563, 2015). "To validate previous findings, we opted to measure the serum C3 expression level among drug-naïve schizophrenia patients and healthy controls." (PMID 26305563, 2015). "Furthermore, elevated expression of central and peripheral complement components C3 and C4 has been reported in patients with generalized anxiety disorder, major depressive disorder, and schizophrenia." (PMID 40896413, 2025).
schizophrenia (continued). "Interestingly, there is evidence of an overactive classical pathway in schizophrenia, including the overexpression of C1q, C3, and C4; conversely, there is weak evidence of reduced levels of these genes in ASD." (PMID 38791517, 2024). "Also, a newly discovered complement C3 and C4 regulator, CUB and Sushi multiple domains 1 (CSMD1), has been placed among the top of genome-wide risk alleles for schizophrenia." (PMID 39022733, 2024). "In addition, C3 and C1q protein levels in the blood are significantly increased in patients with schizophrenia when compared to healthy control subjects." (PMID 39022733, 2024). "Second, complement component factors that have a role in schizophrenia, such as C1q, C3, and C4, may affect the production of IL-23 and IL-17 family members." (PMID 36256663, 2022). "While serum levels of C3 and C4 are increased in drug free patients with established schizophrenia, serum levels of C3 are decreased in medicated patients with established schizophrenia, suggesting a possible effect of antipsychotic treatment on these markers." (PMID 33667853, 2021). "Here, we hypothesized that activators (C1qA) and/or mediators (C3 or C4) of the classical pathway would be elevated in the midbrain of those with schizophrenia compared to controls, especially in those with a high inflammatory biotype." (PMID 33133060, 2020). "However, a recent study showed that increased levels of C3, acting as activation of complement system, can be found in schizophrenia patients when compared with healthy controls." (PMID 26305563, 2015). "Alterations in functional activities of classical, alternative and lectin pathways of complement, a major mediator of the immune response, as well as changes in blood levels and expression profiles of its C1q, C3, and C4 components have been detected in schizophrenia-affected subjects." (PMID 21867543, 2011). "While we found positive correlations between complement transcripts (C1qA and C3) and microglia or astrocyte markers across diagnostic and inflammatory subgroups, the only unique strong positive correlation was between CD163 and C1qA mRNAs in schizophrenia cases with high inflammation." (PMID 33133060, 2020). "Moreover, abnormal peripherals levels of complement proteins such as C4, C1, C1q, C2, C3, C4 and the terminal complement complex (TCC) have been reported in patients with schizophrenia or first episode psychosis." (PMID 33667853, 2021). "In addition, in the blood of schizophrenia affected subjects the levels of circulating immune complexes (CIC) containing natural ligands of CR1, namely C1q and fragments of C3, were also determined." (PMID 21867543, 2011). "However, our findings do not support a straightforward increased level of complement factors in schizophrenia brain, as we do not detect corresponding increases in C3 or C4 complement protein." (PMID 33133060, 2020). "As such, we tested the inflammatory marker CRP, and complement system including C3, C4 and CFH between schizophrenia patients with or without anhedonia." (PMID 37520223, 2023).